HSP90AA1 (heat shock protein 90 alpha family class A member 1)
Diseases named in the same sentence as HSP90AA1 in open-access papers (continued):
Sharing a sentence is not in itself a finding about the gene and the disease.
cancer (continued). "Subsequently, CCK8 assay was utilized to explore the HSP90AA1 impact on the proliferative viability of BC cells, and the growth efficiency of cancer cells was significantly inhibited after HSP90AA1 knockdown." (PMID 38263419, 2024). "This suggests that HSP90AA1 inhibition holds significant promise as a therapeutic approach for cancers, given its central role in regulating key signaling pathways involved in cancer progression." (PMID 39518920, 2024). "Elevated Aha1 levels are correlated with increased HSP90AA1 expression in several cancers and decreased survival." (PMID 39776493, 2024). "Research has shown that targeting HSP90AA1 can lead to inhibition of cancer cell proliferation and survival, making it a potential therapeutic target." (PMID 38785796, 2024). "In this study, we demonstrated that AE downregulates HSP90AA1, a critical protein involved in cancer cell survival." (PMID 39518920, 2024). "The expression of YWHAG and HSP90AA1 was significantly correlated in 21 cancer types from the TCGA database." (PMID 37759388, 2023). "A study found a correlation between poorer overall survival and higher expression of HSP90AA1 in cancer tissues." (PMID 37764733, 2023). "Elevated expression of HSPA4 and HSP90AA1 is related with poor clinical outcomes in cancer patients." (PMID 37033966, 2023). "The results of previous studies have confirmed that SLC41A3, SEC61A1, LRP4, PPM1G, and HSP90AA1 play important roles in cancer progression." (PMID 35799605, 2022). "At the protein level, the expression levels of EGFR, HSP90AA1, and mTOR were significantly different between normal and cancer tissues (all p < 0.05)." (PMID 36569844, 2022). "Considering that AHSA1 is an ATPase activator of HSP90AA1, we analyzed the expression of HSP90AA1 in pan-cancer." (PMID 35757728, 2022). "Cox regression analysis showed that HSP90AA1 expression was significantly correlated with OS in 6 of the 32 cancers (marked in red), including LIHC, KIRC, HNSC, LUAD, BRCA and MESO." (PMID 36158677, 2022). "The genes MAPK14, HSP90AA1, PTGS2, and ESR1 have been linked to cancer, infection, and immune disease." (PMID 36212968, 2022). "Pan-cancer analysis and clinical data analysis provided a better understanding of the differences in HSP90AA1 gene and HSP90α protein expression in plasma and tissues of different cancers." (PMID 36158677, 2022). "Studies have shown that DAB2IP inhibits cancer progression, while HSP90AA1 promotes cancer progression." (PMID 35590292, 2022). "The HSP90AA1 expression exhibited strong correlations with immune checkpoint genes according to pan-cancer analysis." (PMID 36158677, 2022). "MAPK14, hSP90AA1, and PTGS2 genes are associated with apoptotic biological processes, TNF signaling pathways, toll-like receptor signaling pathways, and cancer pathways." (PMID 36212968, 2022). "The expression of HSP90AA1 in 32 malignant tumor tissues in CCLE database was consistent with that in TGCA database." (PMID 36158677, 2022). "Pan-cancer analysis showed that HSP90AA1 was highly expressed in 27 of 33 tumors, but low in individual cancers (such as renal malignancies)." (PMID 36158677, 2022). "HSP90AA1 is a key heat shock protein involved in promoting tumor transformation and cancer development." (PMID 35899228, 2022).
cancer (continued). "More importantly, many client proteins of HSP90AA1 were involved in tumor pathogenesis, so HSP90AA1 played an important role in regulating the cancer cells’ growth and survival." (PMID 36159817, 2022). "HSP90AA1 is expressed in tumors and can activates many oncogenic proteins, thereby stimulating cancer cell survival, proliferaton, and invasiveness." (PMID 35754840, 2022). "Canonical CTNNB1 p.Ser45Pro missense mutation, as well as several other cancer-related genes (e.g., PML, HSP90AA1, BAZ1A, ARHGAP5, LHFPL6), were detected in the PT sample." (PMID 35860547, 2022). "Recent studies reported that HSP90AA1 expression levels are upregulated in tissue and plasma of several cancers and correlated with poor prognosis." (PMID 35352023, 2022). "Cox regression analysis showed that HSP90AA1 expression was significantly correlated with OS in only 6 of the 32 cancers, including LIHC, KIRC, HNSC, LUAD, BRCA and MESO." (PMID 36158677, 2022). "Prostaglandin G/H synthase 2 (PTGS2) exhibits the highest degree and regulates 13 types of cancers, followed by HSP90AA1 (degree = 12), EGFR (degree = 12), and MMP2 (degree = 11)." (PMID 34248628, 2021). "HSP90AA1 can act on the functions in invasion and migration of cancer cells, and it is closely related to poor prognosis of tumors." (PMID 34311656, 2021). "Recently, some studies have indicated that overexpression of HSP90AA1 is related to various malignant tumors." (PMID 34109171, 2021). "HSPA1 in cancer cells and, to lesser degree, HSP90AA1 can be reduced by oxicam analogues with thiazine ring substituted via propylene linker by arylpiperazine pharmacophore with fluorine substituents and by benzoyl moiety." (PMID 34827586, 2021). "HSP90AA1, a 90-kDa heat shock protein, is an important target for cancer treatment because it can stabilize several cancer-related client proteins essential for tumor progression, such as AKT, PIM1, and HIF1A." (PMID 34194515, 2021). "The higher expression of HSP90AA1 in cancer tissues correlated with poorer overall survival was observed." (PMID 35095481, 2021). "Previous research has demonstrated that in cancer cells, HSP90AA1 activates many oncogenic client proteins, thereby stimulating cell survival, growth, and invasiveness." (PMID 34109171, 2021). "To investigate the function of HSP90AA1 in PDAC cluster 2 cancer cells, we silenced HSP90AA1 in human PDAC cell line PATU8988 and mouse PDAC cell line KPC C2 by stably expressing short hairpin RNA (shRNA)." (PMID 33658487, 2021). "The expressions of five HSPs members (HSPH1, HSPD1, SERPINH1, HSPA4 and HSP90AA1) in more than 20 types of cancers were detected and compared with expressions in normal tissues using the ONCOMINE database." (PMID 32523426, 2020). "Altogether, we propose that NANOG+ cancer cells enriched by immunoediting drive preferential expression of HSP90AA1 via transcriptional regulation and undergo HSP90A accumulation in tumor cells." (PMID 31992715, 2020). "HSP90AA1, also known as eHsp90α, has been reported to promote tumor cell metastasis and tumor motility in different types of cancer, including IBC59." (PMID 33020551, 2020). "Conversely, the high expression of other four HSPs (HSP90AA1, CCT1, CCT2, CCT6A) was associated with poor prognosis (survival Z-score > 0) for most types of cancer." (PMID 31101846, 2019). "Recently, studies found that HSP90AA1 is expressed extracellularly and involved in tumor progression and cancer cell invasion." (PMID 30153855, 2018). "It is well-known that several HSPs have clinical correlates, the best example is probably HSP90AA1 that it is used as an adverse prognostic factor not only in BRCA but also in other cancers." (PMID 29954368, 2018). "The 90-kDa heat shock protein HSP90AA1 is critical for the stability of several proteins that are important for tumor progression and thus, is a promising target for cancer therapy." (PMID 25167922, 2014).
cancer (continued). "2-24a/Cu induced the decrease of HSP90AA1 in cancer cells, which is a crucial protein for cancer cell survival." (PMID 25167922, 2014). "HSP90AA1, a chaperone protein that assists the folding and maturation of its client proteins, is an alternative therapeutic target for cancer therapy." (PMID 25375091, 2014). "AKT1, another client protein of HSP90AA1, is crucial for survival and proliferation of cancer cells." (PMID 25167922, 2014). "HSP90AA1 is critical for cancer cell metabolism and signal transduction pathways, and inhibition of HSP90AA1 is a promising strategy for cancer therapy." (PMID 25167922, 2014). "Patient-derived tumor-like HSP90AA1 is a key protein in the cancer pathway, prostate cancer pathway and PI3K-Akt signaling pathway, and it also belongs to the HSP90 family, which interacts with various co-chaperones to regulate its substrate recognition, ATPase cycle and chaperone function." (PMID 40230723, 2025). "Future research on the sustained active expression or inhibition of IFI6 and similar downstream molecules associated with HSP90AA1 in EGFR mutant LUAD and other cancer subtypes is also crucial for advancing our understanding of tumor stress responses and resistance." (PMID 40234395, 2025). "Overall, we first discovered that NF retards CC‐induced muscle atrophy by regulating AKT–mTOR and NF‐κB signalling pathways through directly binding HSP90AA1, suggesting that NF may be an effective treatment for cancer cachexia." (PMID 40170230, 2025). "HSP90AA1 plays a key role in stabilizing oncogenic proteins and promoting cancer progression." (PMID 41300430, 2025). "Similarly, HSP90AA1 is known to enhance tumor aggressiveness, while PTGS2 (encoding COX-2) promotes apoptosis resistance, proliferation, inflammation, and metastasis of cancer cells." (PMID 40573291, 2025). "By binding to HSP90AA1, C3G may disrupt the chaperone’s function, leading to the destabilization of critical oncoproteins and ultimately inhibiting cancer cell survival and proliferation." (PMID 40141751, 2025). "In cancer cells, HSP90AA1 is often overactivated, contributing to tumor growth and survival." (PMID 41465428, 2025). "Crucially, upon evaluating genes that may significantly influence cancer prognosis, HSP90AA1, HSPA8, DNAJB1, and HSP90AB1 manifested pronounced correlations with HSPA4 expression." (PMID 38305786, 2024). "These proteins are frequently co-regulated in various cancer contexts, and their overlapping roles may limit the specificity of targeting HSP90AA1 alone." (PMID 39518920, 2024). "Besides, HSP90AA1 participates in tumor progression and cancer cell invasion, and is known to promote cancer cell proliferation and metastasis." (PMID 38685981, 2024). "In the same way as Hsp90AA1, Hsp90B1, an endoplasmic reticulum-localized subtype of Hsp90, interacts with a variety of pro-survival and mitogenic proteins to facilitate the growth and spread of cancer." (PMID 38892035, 2024). "At the same time, it has also been reported that HSP90AA1 may promote malignant tumor LM by regulating EMT." (PMID 37547757, 2023). "HSP90AA1, HSP90AB1, and HSP90B1 have been associated with a poor prognosis of tumors, and upregulation of TRAP1 promotes the growth and progression of various cancers." (PMID 37569852, 2023). "However, the specific molecular mechanism of EMT in HPSCC and the role of HSP90AA1 in regulating EMT in cancer cells are areas that warrant further exploration." (PMID 37547757, 2023). "Studies have shown that HSP90AA1 enhances the proliferation and invasion of tumor cells, further worsening the disease, and that HSP90AA1 may be a potential target for the treatment of cancer." (PMID 36874006, 2023). "Next, we further validated the expression of HSP90AA1 in these 32 cancer types using CCLE database." (PMID 36158677, 2022). "HSP90AA1 is an essential molecular chaperone overexpressed in tumors that could serve as a cancer biomarker." (PMID 36500393, 2022).
cancer (continued). "Upregulation of HSP90AA1 is related to poor overall survival in cancer patients." (PMID 36437827, 2022). "Importantly, among three miRNAs, only miR-570 showed partial complemental with 3′-UTR sequences in not only human HSPA1A and BAG3 but also HSPA1B and HSP90AA1 (highlighted in red), which are involved in cancer progression." (PMID 36114410, 2022). "Next, survival analysis for HSP90AA1 in human cancer was conducted." (PMID 36158677, 2022). "It was reported that HSP90AA1 could affect the survival of tumor cells, the invasion and migration of cancer cells, and was closely related to the poor prognosis of tumours." (PMID 35411258, 2022). "Apart from CTNNB1, we’ve identified several cancer-related gene mutations, including PML, HSP90AA1, BAZ1A, ARHGAP5, LHFPL6 in the primary tumor of HB, which may also contribute to the carcinogenesis of HB." (PMID 35860547, 2022). "HSP90AA1 is also a potential molecular target in cancer therapy." (PMID 35754840, 2022). "The expression of HSPA1 and HSP90AA1, key heat shock proteins involved in facilitating neoplastic transformation and cancer development, is altered already in precancerous colorectal lesions and surrounding tissue, to degree dependent on polyp potential for malignancy." (PMID 34827586, 2021). "Studies have suggested that HSP90AA1, HSP90AB1 gene products, and their associated chaperon proteins (Aha1, Cdc37, p23, and Tpr2) as well as HSP90-dependent transcription factor HSF1 are overexpressed in a variety of cancers." (PMID 34109171, 2021). "Our study revealed that appropriate use of pretreatment plasma HSP90AA1 levels in combination with other markers could more effectively predict the patient’s cancer and metastasis rates." (PMID 34109171, 2021). "There are 473 genes uniquely positively correlated with HSP90AA1 in cancer patients." (PMID 35095481, 2021). "Low levels of HSP90AB1/TRAP1, HSPA6/TRAP1, and HSP90AA1/TRAP1 in urine increase the probability of the patient having cancer, whereas low levels of CCT2/HSP90AB1 and HSPB1*HSPA9 in urine are strongly associated with non-cancer groups." (PMID 34692733, 2021). "Based on the role of HSP90AA1 in cancer progression, we hypothesized that ZNRD1-AS1 may play a role through the miR-9-5p/HSP90AA1 axis." (PMID 34226297, 2021). "Some studies demonstrated that HSP90AA1 is closely related to a variety of malignant tumors." (PMID 34557405, 2021). "HSP90AA1 can exert its tumor-promoting effect by stabilizing c-MYC protein in several cancer types." (PMID 32576198, 2020). "Interestingly, we found that level of NANOG-responsive genes and HSP90AA1 within tumor inversely correlated with T cell infiltration in various cancer patients from TCGA, suggesting NANOG–HSP90A axis in tumor cells induces ICB therapeutic resistance." (PMID 31992715, 2020). "Some of these targets are oncogenes, for example, CCND1 and KRAS, or tumour suppressors such as PTEN and HSP90AA1, and the deregulation of these genes may contribute to cancer pathogenesis." (PMID 30845775, 2019). "It has been reported that HSP90AA1 is critical to the survival and proliferation of cancer." (PMID 30868054, 2019). "More specifically, genes ENO1, H3F3B and HSP90AA1 are important cancer drivers in human cells." (PMID 29882813, 2018). "It is not known whether oxidative stress generated by copper complexes can regulate the expression of HSP90AA1 in cancer cells." (PMID 25167922, 2014).
cancer (continued). "As HSP90AA1 protein was significantly decreased in the 2-24a/Cu-treated cancer cells, we next investigated whether the client proteins of HSP90AA1 were also degraded in cancer cells." (PMID 25167922, 2014). "By decreasing the abundance of HSP90AA1 in cancer cells, 2-24a/Cu could decrease the stability of HSP90AA1 client proteins, many of which are critical in tumor initiation and metastasis." (PMID 25167922, 2014). "As heat shock family proteins play an important role in the survival of cancer cells, we investigated whether the protein abundance of HSP90AA1 was also increased in the 2-24a/Cu-treated cells." (PMID 25167922, 2014). "However, it has been reported that ROS generated by vitamin C and K3 can induce degradation of HSP90AA1, and therefore contributes to inducing cancer cell death." (PMID 25167922, 2014). "Furthermore, several studies have demonstrated that HSP90AA1 inhibitors decrease VEGF secretion from cancer cells, impair endothelial cell tubule formation in vitro, and reduce tumor size and vascularization in vivo." (PMID 25375091, 2014). "HSP90AA1, heat shock protein 90α Family Class A Member 1, is a highly conserved chaperone protein across species, which plays an important role in cell cycle regulation, gene modification, regulation of DNA damage and the onset and progression of various human cancers." (PMID 40170230, 2025). "This implies that RA may reduce cancer cell survival by blocking HSP90AA1’s carcinogenic activity." (PMID 40427522, 2025). "Furthermore, molecular dynamics simulations of the HSP90AA1-C3G complex demonstrated stable binding and structural integrity, suggesting that C3G may inhibit HSP90AA1, a protein involved in cancer progression." (PMID 40141751, 2025). "Moreover, the role of HSP90AA1 in cancer pathogenesis is a hot topic of research right now." (PMID 35330393, 2022). "Interestingly, the similar results were observed for HSP90AA1 expression in pan-cancer." (PMID 35757728, 2022). "Importantly, the proteins encoded by HSP90AA1 and HSP90AB1 genes act in several pivotal roles in the cancer development through other relevant signaling pathways identified in this study, such as the ones involving the aryl hydrocarbon receptor (AhR), glucocorticoid receptor and nitric oxide (NO)." (PMID 33656060, 2021). "Thus, inhibition of HSP90AA1 might affect cancer cells growth and survival from multiple pathways, making HSP90AA1 a promising anti-tumor drug target." (PMID 32576198, 2020). "The six thermogenes include HSP90AA1 and HSPA4, common in thermoresistance and DAMPs/ICD, DNAJB5, the protein product of which has the highest estimated thermostability, and HSPA1A, HSP90AB1, and BAG1, which are implicated in cancer-relevant pathways (underlined)." (PMID 31814876, 2019). "Network toxicology indicated that AEF modulates targets such as SRC, AKT, and HSP90AA1, thereby influencing pathways including the PI3K-AKT signaling pathway and pathways in cancer." (PMID 42043040, 2026). "Overexpression of HSP90AA1 and HSP90AB1 can affect cancer cell viability and provide an escape mechanism from treatment-induced apoptosis." (PMID 39888956, 2025). "It is important to note that while HSP90AA1 is a common survival gene, UVM exhibits a unique ‘Chaperone Dependency’ distinct from other cancers." (PMID 41567202, 2025). "By leveraging RNA sequencing, network pharmacology, molecular docking, and molecular dynamics, this study has elucidated how bioactive metabolites like C3G and ursolic acid interact with key cancer-related proteins, such as PTGS2, HSP90AA1, and ERBB2." (PMID 40141751, 2025).